ERCC6 (ERCC excision repair 6, chromatin remodeling factor)
Description:
Essential factor involved in transcription-coupled nucleotide excision repair (TC-NER), a process during which RNA polymerase II-blocking lesions are rapidly removed from the transcribed strand of active genes. Plays a central role in the initiation of the TC-NER process: specifically recognizes and binds RNA polymerase II stalled at a lesion, and mediates recruitment of ERCC8/CSA, initiating DNA damage excision by TFIIH recruitment. Upon DNA-binding, it locally modifies DNA conformation by wrapping the DNA around itself, thereby modifying the interface between stalled RNA polymerase II and DNA. Acts as a chromatin remodeler at DSBs; DNA-dependent ATPase-dependent activity is essential for this function. Plays an important role in regulating the choice of the DNA double-strand breaks (DSBs) repair pathway and G2/M checkpoint activation; DNA-dependent ATPase activity is essential for this function. Regulates the DNA repair pathway choice by inhibiting non-homologous end joining (NHEJ), thereby promoting the homologous recombination (HR)-mediated repair of DSBs during the S/G2 phases of the cell cycle. Mediates the activation of the ATM- and CHEK2-dependent DNA damage responses thus preventing premature entry of cells into mitosis following the induction of DNA DSBs. Remodels chromatin by evicting histones from chromatin flanking DSBs, limiting RIF1 accumulation at DSBs thereby promoting BRCA1-mediated HR. Required for stable recruitment of ELOA and CUL5 to DNA damage sites. Also involved in UV-induced translocation of ERCC8 to the nuclear matrix. Essential for neuronal differentiation and neuritogenesis; regulates transcription and chromatin remodeling activities required during neurogenesis. Involved in repair of DNA damage following UV irradiation, acting either in the absence of ERCC6 or synergistically with ERCC6. Involved in the regulation of gene expression. In the absence of ERCC6, induces the expression of genes characteristic of interferon-like antiviral responses. This response is almost completely suppressed in the presence of ERCC6. In the presence of ERCC6, regulates the expression of genes involved in metabolism regulation, including IGFBP5 and IGFBP7. In vitro binds to PGBD3-related transposable elements, called MER85s; these non-autonomous 140 bp elements are characterized by the presence of PGBD3 terminal inverted repeats and the absence of internal transposase ORF.
Synonyms: CSB; RAD26; ARMD5; CKN2; COFS; COFS1; CSB-PGBD3; POF11; UVSS1
Tractability: Small molecule: a structure with a bound ligand is known. PROTAC: UniProt records ubiquitination sites on it; ubiquitination databases record sites on it; its protein half-life has been measured.
Gene: Protein-coding gene on chromosome 10 (49,454,168 to 49,539,538, reverse strand). Ensembl gene ENSG00000225830.
Subcellular location: Nucleus; Chromosome
Subcellular location (Human Protein Atlas): Nucleoplasm; Nuclear bodies
Pathways (Reactome):
DNA Repair: Dual incision in TC-NER; Formation of TC-NER Pre-Incision Complex; Gap-filling DNA repair synthesis and ligation in TC-NER; Transcription-Coupled Nucleotide Excision Repair (TC-NER)
Gene expression (Transcription): B-WICH complex positively regulates rRNA expression; ERCC6 (CSB) and EHMT2 (G9a) positively regulate rRNA expression; RNA Polymerase I Transcription Initiation
Gene Ontology:
Molecular function: ATP binding; ATP hydrolysis activity; ATP-dependent activity, acting on DNA; ATP-dependent chromatin remodeler activity; ATP-dependent DNA damage sensor activity; chromatin binding; chromatin-protein adaptor activity; DNA binding; DNA helicase activity; protein binding; protein tyrosine kinase activator activity
Biological process: base-excision repair; DNA damage checkpoint signaling; double-strand break repair via classical nonhomologous end joining; negative regulation of double-strand break repair via nonhomologous end joining; neurogenesis; neuron differentiation; neuron projection development; positive regulation of DNA repair; positive regulation of DNA-templated transcription, elongation; positive regulation of double-strand break repair via homologous recombination; positive regulation of transcription by RNA polymerase III; protein localization to chromatin; regulation of DNA-templated transcription elongation; response to oxidative stress; single strand break repair; transcription-coupled nucleotide-excision repair; chromatin remodeling; positive regulation of transcription by RNA polymerase I; positive regulation of transcription by RNA polymerase II; transcription by RNA polymerase II; DNA protection; DNA repair; regulation of transcription elongation by RNA polymerase II
Cellular component: B-WICH complex; chromosome; nuclear body; nucleolus; nucleoplasm; nucleus; site of DNA damage; transcription elongation factor complex
Genetic constraint (gnomAD): Loss-of-function variants: 105 observed, 153.79 expected, observed/expected ratio (o/e) 0.68, 90% interval 0.58 to 0.8. The upper end of that interval is the gene's LOEUF score, 0.8, which puts it in group 3 of 6, group 1 being the genes least tolerant of losing a copy. Missense variants: 1,635 observed, 1,837.4 expected, observed/expected ratio (o/e) 0.89, 90% interval 0.85 to 0.93. Synonymous variants: 666 observed, 676.74 expected, observed/expected ratio (o/e) 0.98, 90% interval 0.92 to 1.05.
Gene-disease validity (ClinGen):
ClinGen rates the evidence that ERCC6 causes each of these diseases.
Cockayne spectrum with or without cerebrooculofacioskeletal syndrome (autosomal recessive): Definitive. An autosomal recessive, multisystem condition caused by pathogenic variants of the ERCC6 gene, encoding the DNA excision repair protein, ERCC-6.
Homologues: Orthologues: chimpanzee ERCC6 (99% identical), macaque ERCC6 (97% identical), dog ERCC6 (84% identical), mouse Ercc6 (79% identical), rat Ercc6 (78% identical), rabbit ERCC6 (76% identical), guinea pig ERCC6 (75% identical), tropical clawed frog ercc6 (58% identical), zebrafish ercc6 (57% identical). Paralogues in human: CHD7 (19% identical), SRCAP (19% identical), CHD9 (18% identical), SMARCA4 (18% identical), CHD4 (18% identical), CHD5 (18% identical), CHD3 (18% identical), EP400 (18% identical), BTAF1 (18% identical), CHD8 (17% identical), SMARCA2 (17% identical), CHD2 (17% identical), and 18 more.
Diseases named in the same sentence as ERCC6 in open-access papers:
ERCC6 is named in the same sentence as 70 diseases in open-access papers, as found by Europe PMC text mining. Sharing a sentence is not in itself a finding about the gene and the disease. The quoted sentences say what the papers report.
Cockayne syndrome (54 papers, 2010 to 2026). A multisystem condition characterized by short stature, a characteristic facial appearance, premature aging, photosensitivity, progressive neurological dysfunction, and intellectual deficit. "Mutations in ERCC6 lead to Cockayne Syndrome and other neurodegenerative disorders, but some variants, such as M1097V, have been associated with cancer risk, particularly prostate cancer (PCa) in African Americans (AAs) in Louisiana." (PMID 41709957, 2026). "Cockayne Syndrome (CS) is an autosomal recessive disorder arising from mutations in either of two disease‐associated genes, ERCC6 or ERCC8." (PMID 40536083, 2025). "Approximately 70% of all CS cases carry ERCC6 mutations; therefore, this review will focus solely on Cockayne Syndrome complementation group B (CS‐B)." (PMID 40536083, 2025). "Cockayne syndrome (CS), a rare hereditary neurodegenerative disorder caused by pathogenic variants in ERCC6 (CSB) and ERCC8 (CSA), often clinically overlaps with cerebral palsy (CP), leading to misdiagnosis." (PMID 40842628, 2025). "This review will focus solely on Cockayne Syndrome complementation group B (CS‐B), considering that approximately 70% of CS patients have a mutation in the ERCC6 gene." (PMID 40536083, 2025). "Cockayne syndrome (CS) is a rare hereditary progeria that is compromised in handling such situations, caused by mutations in either the ERCC6/CSB gene or the ERCC8/CSA gene." (PMID 39704188, 2025). "Perhaps the best-studied chromatin remodeling protein involved in rDNA regulation is Cockayne syndrome B (encoded by the gene ERCC6), which is the major gene that is mutated in Cockayne syndrome (CS)." (PMID 40004235, 2025). "The ERCC6 gene encodes a multifunctional protein called Cockayne syndrome B (CSB) that belongs to the SWI2/SNF2 family, which is involved in damaged DNA repair, chromatin remodeling, and transcription." (PMID 41459025, 2025). "Mutations in the ERCC6 and ERCC8 genes are the predominant causes of Cockayne syndrome, with ERCC6 gene mutations present in approximately 75% of cases." (PMID 39473441, 2024). "It is caused by mutations in ERCC6 or ERCC8 encoding for Cockayne syndrome B (CSB) and A (CSA) proteins, respectively." (PMID 39209536, 2024). "Cockayne syndrome B (CSB, also known as ERCC6) protein is apparently involved, since cells from Cockayne syndrome B patients are deficient in their ability to clear 8-oxoA." (PMID 38279342, 2024). "CSB exhibits severe neurological defects caused by a mutation in ERCC6 (also known as Cockayne syndrome B, CSB)." (PMID 39702477, 2024). "The c.1992+3A>G variant in the ERCC6 gene encoding the DNA excision repair protein Cockayne syndrome B (CSB) was previously reported in the six members of another Turkish family with similar clinical findings." (PMID 40225931, 2024). "The loss-of-function mutations in ERCC8 and ERCC6 genes occurring in Cockayne syndrome patients prevent the removal of these bulky DNA lesions by TC-NER." (PMID 39209536, 2024). "ERCC6L2 has 30% identity to ERCC6 at the protein level, the causal gene for Cockayne Syndrome B (CSB)." (PMID 35812759, 2022). "Impaired TC-NER is considered to be an underlying cause of photosensitivity seen in clinical cases of Cockayne syndrome (CS), the majority of which are caused by germline mutations of the ERCC6 gene encoding CSB." (PMID 33806087, 2021). "Pathogenic variants in ERCC6 are associated with Cockayne Syndrome, which is an autosomal recessive disorder and characterized by postnatal developmental failure, progressive neurodegeneration, microcephaly, and premature aging." (PMID 34809627, 2021). "In this study, the WES test of the proband identified the homozygous missense mutation c.1607T>G (p.Leu536Trp) in the ERCC6 gene, which supported the clinical diagnosis of Cockayne syndrome B in our case." (PMID 34833108, 2021).
Cockayne syndrome (continued). "One study demonstrated Cockayne syndrome B in three Chinese sisters carrying compound heterozygous missense mutations of c.1595A>G (p.Asp532Gly) and c.1607T>G (p.Leu536Trp) in the ERCC6 gene." (PMID 34833108, 2021). "Another study identified Cockayne syndrome B in two Chinese brothers carrying compound heterozygous missense mutations of c.1357C>T (p.Arg453Ter) and c.1607T>G (p.Leu536Trp) in the ERCC6 gene." (PMID 34833108, 2021). "Approximately 62–75% of all CS cases had mutations in the ERCC6 gene, which defined them as Cockayne syndrome B (CSB)." (PMID 34833108, 2021). "Cockayne syndrome is a neurodegenerative disease caused by the mutation in either Cockayne syndrome A (CSA/ERCC8) or Cockayne syndrome B (CSB/ERCC6) genes, which leads to impaired transcription-coupled NER." (PMID 32605254, 2020). "Another report identified two novel ERCC6 mutations (a splice-site mutation, c.2709+1G>T, in intron 14 and a short deletion in exon 5 (c.1293_1320del) in an Amish individual with Cockayne’s syndrome." (PMID 25463447, 2014). "A classic Cockayne’s syndrome case has been reported carrying a novel homozygous nonsense mutation c.1387C>T/Q463X in the ERCC6 gene." (PMID 25463447, 2014). "Mutations of the ERCC6 and ERCC8 genes are the predominant cause of Cockayne syndrome, and the ERCC6 gene mutation is present in approximately 65% of cases." (PMID 25463447, 2014). "The present study reports two ERCC6 mutations identified by whole exome sequencing in three individuals with Cockayne syndrome from a Chinese family." (PMID 25463447, 2014). "Loss of function mutations in ERCC6 cause the autosomal recessive disorder Cockayne syndrome, which includes many severe physical and neurologic features, with premature aging and retinopathy as hallmarks of the disease." (PMID 21072178, 2010). "The ERCC6 gene is involved in DNA repair, and loss of function mutations in this gene cause Cockayne syndrome (CS)." (PMID 21072178, 2010). "Cockayne Syndrome is an autosomal recessive disorder that arises from mutations in one of two distinct genes: (i) excision repair cross‐complementing protein group 6 (ERCC6/CSB) or excision repair cross‐complementing protein group 8 (ERCC8/CSA), located in chromosomes 10q11 and 5q11, respectively." (PMID 40536083, 2025). "We also detected one case each (2.5% of total abnormalities) of Wilson’s disease (mutations in ATP7B), cystic fibrosis (mutations in CFTR), Cockayne syndrome (mutations in ERCC6), auditory neuropathy (mutations in OTOF), and autosomal recessive polycystic kidney disease (mutations in PKHD1)." (PMID 41329681, 2025). "Given that the index affected individual was assumed to have typical Cockayne syndrome and the diagnostic yield of sequencing both genes in such cases is close to 100%,18 the prior probability that a single detected ERCC6 variant on each allele is the cause of the phenotype in this family was 70%." (PMID 38103548, 2024). "Cockayne Syndrome is a genetically heterogeneous disorder partially overlapping with Xeroderma Pigmentosum caused by biallelic mutations in genes regulating DNA repair (ERCC6, ERCC8)." (PMID 36862146, 2023). "Cockayne Syndrome (CS) has three subtypes: caused by mutations in either ERCC6 (CSB), ERCC8 (CSA), and an as-yet unknown third gene." (PMID 35812759, 2022). "Germline mutations in the ERCC6 gene are responsible for the majority of clinical cases of Cockayne syndrome, which is characterized by severe photosensitivity, severe impairment of physical development, progressive neurological degeneration, cataracts, hearing loss, and segmental premature ageing." (PMID 36142121, 2022). "Cockayne syndrome is divided into two categories by the mutations in the ERCC6 and ERCC8 genes." (PMID 34833108, 2021). "Cockayne syndrome (CS) is a rare disease caused by mutations in ERCC6/CSB or ERCC8/CSA." (PMID 34946871, 2021).
Cockayne syndrome (continued). "In addition, hypomyelination was characterized in Cockayne syndrome, another disorder with ERCC6 and ERCC8 mutations also causing defective DNA repair after UV damage." (PMID 29451896, 2018). "Mutations in ERCC6 gene may lead to Cockayne syndrome, which often presents as severe cataract and AMD." (PMID 29689049, 2018). "The present report describes a case of Cockayne syndrome in a Chinese family, with the patients carrying two missense mutations (c.1595A>G, p.Asp532Gly and c.1607T>G, p.Leu536Trp) in the ERCC6 gene in an apparently compound heterozygote status, especially, p.Asp532Gly has never been reported." (PMID 25463447, 2014). "Among these disorders are Cockayne syndrome which is caused by mutations in ERCC6 (CSB) or ERCC8 (CSA), trichothiodystrophy (TTD) caused by mutations in ERCC2 (XPD), ERCC3 (XPB), or TTDA (GTF2H5) and XPF-ERCC1 progeria (XFE) caused by dysfunction of the XPF-ERCC1 heterodimer." (PMID 23947592, 2013). "ERCC6 is involved in DNA repair and mutations in ERCC6 cause Cockayne syndrome (CS)." (PMID 21072178, 2010). "Cockayne syndrome (CS) is an autosomal recessive multisystem degenerative disorder caused by the mutations in two complementary genes, namely the excision repair cross-complementation group 6 (ERCC6) (80%) and the excision repair cross-complementation group 8 (ERCC8) (20%)." (PMID 36077104, 2022). "Cockayne Syndrome (CS) is a rare autosomal recessive genetic disease, mainly caused by ERCC8 and ERCC6 gene defect." (PMID 41299792, 2025). "CS is caused by mutations in the ERCC6 and ERCC8 genes coding for Cockayne Syndrome group B protein (CSB) (accounting for 80% of cases) and Cockayne Syndrome group A protein (CSA) (accounting for approximately 20% of the cases), respectively." (PMID 36979413, 2023). "Based on her phenotypic features of suspected Cockayne syndrome we performed Sanger sequencing of the ERCC6 gene which is located in the chromosomal locus 10q11.23." (PMID 31337399, 2019). "TFII-I interacted with genes encoding for the heme-regulated eIF2α kinase HRI (EIF2AK1), the Cockayne syndrome-B (CS-B or ERCC6), heterochromatin protein 1 beta (Hp1 beta, CBX1) and TF ATF3." (PMID 24875474, 2014). "Mutations in the ERCC6 and ERCC8 genes are known to cause Cockayne syndrome and approximately 65% individuals with CS have mutations in the ERCC6 gene." (PMID 25463447, 2014). "Cockayne syndrome (CS) is a rare progeroid disorder characterized by growth failure, microcephaly, photosensitivity, and premature aging, mainly arising from biallelic ERCC8 (CS-A) or ERCC6 (CS-B) variants." (PMID 35748794, 2022). "ERCC6, a gene involved in preferential repair, is generally closely related to Cockayne’s syndrome." (PMID 35912179, 2022). "In summary, we described a Taiwanese boy with Cockayne syndrome presenting novel homozygous missense mutation c.1607T>G (p.Leu536Trp) in the ERCC6 gene, which has not been reported before." (PMID 34833108, 2021). "Conversely, mutation in TCR genes ERCC8 (CSA) and ERCC6 (CSB) result in Cockayne’s syndrome that is characterised by neurological abnormalities but no increase in skin cancer incidence." (PMID 26913219, 2015). "ERCC6, also known as CSB (Cockayne Syndrome B), is a key protein involved in transcription-coupled nucleotide excision repair (TC-NER), a DNA repair process that removes lesions blocking RNA polymerase." (PMID 41709957, 2026). "Accordingly, ERCC6 was the first human TC-NER gene identified, based on its capacity to rescue the UV-sensitive phenotype of Cockayne syndrome complementation group B." (PMID 40723898, 2025). "The transcription-coupled NER (TC-NER) removes stalled RNA polymerase and repairs these damages, initiating by the Cockayne syndrome proteins CSA and CSB/ERCC6." (PMID 34066883, 2021). "A major challenge in this field is that mutations of the Cockayne syndrome‐associated genes, ERCC8 and ERCC6, do not recapitulate features of the human disorder in mice." (PMID 35834102, 2022).